OASL (2'-5'-oligoadenylate synthetase like)
Diseases named in the same sentence as OASL in open-access papers (continued):
Sharing a sentence is not in itself a finding about the gene and the disease.
vasculitis (1 paper, 2014). "Gene expression of OASL was higher in HCV MC vasculitis patients compared to the other subject cohorts [2.20 ± 0.50 (NV), 4.30 ± 0.90 (HCV MC-Vasc), 2.20 ± 0.80 (HCV), 2.70 ± 0.40 (HIV/HCV); p = 0.02 between HCV MC-Vasc and HCV viremic]." (PMID 24904592, 2014).
Werner syndrome (1 paper, 2018). "Similar to senescent NHDFs, fibroblasts from a patient with Werner syndrome also showed higher expression levels of the ISGs, IFIT3, OASL, ISG15, Mx2, and IFIT27, even at earlier passages." (PMID 30455980, 2018).
infection (101 papers, 2010 to 2026). The state of being infected such as from the introduction of a foreign agent such as serum, vaccine, antigenic substance or organism. "OAS1, OAS2, OAS3, and OASL expression levels are also directly linked to mycobacterial pathogenicity during the early post-infection period, as they can restrict MTB intracellular replication in macrophages by regulating cytokine secretion." (PMID 34490145, 2021). "Previous studies showed significant association between OAS2, OAS3, and OASL expression and IFNα level during infection of virus or bacteria." (PMID 32321151, 2020). "This suggests an underestimated role of OASL in the innate immune response to infection with a variety of pathogens and points to OASL-associated modulation of the type I IFN response." (PMID 28580319, 2017). "Vacuolar pathogenic microbes such as mycobacteria induce OASL early post infection, where it functions in a prosurvival fashion by inhibiting autophagic mechanisms and antimicrobial peptide expression." (PMID 28580319, 2017). "Among the DEGs, OASL, encoding 2’-5’-oligoadenylate synthetase-like protein, was significantly over-expressed from 3 to 8 hours post-infection (fold change=42.5, corrected p-value <0.001)." (PMID 28938587, 2017). "OASL rs3213545 was significantly associated with both symptomatic infection (dominant: OR = 0.72 [95% CI 0.56–0.93], p = 0.012, recessive: OR = 0.45 [95% CI 0.27–0.77], p = 0.003) and WNE/P (dominant: OR = 0.56 [95% CI 0.38–0.81], p = 0.002, recessive: OR = 0.20 [95% CI 0.06–0.65], p = 0.003)." (PMID 21935451, 2011). "According to the previous study, the identified 6 genes were found to be common in all three levels of infection whose expressionlevel increases with the increase in the level of infection (OASL, IFI27, IFIT1, IFIT3, RSAD2 and IFI44L)." (PMID 40322700, 2025). "We identified 6 genes found to be common in all three levels of infection whose expression level increases withthe increase in the level of infection (OASL, IFI27, IFIT1, IFIT3, RSAD2, IFI44L)." (PMID 40255307, 2025). "For this purpose, PBE cells were challenged with SIV H1N1 or H3N2 and the expression of IFN-β and the antiviral factors Mx1, Mx2, IFITM1, OAS1, OAS2, and OASL were evaluated at different hours post-infection." (PMID 40565228, 2025). "Overall, OASL’s regulation in GF animals appears markedly altered both at homoeostasis and infection, emphasising its dependence upon positive microbial signals coming from the GM in the chicken." (PMID 39300162, 2024). "Only five DEPs were common for both infections in both upper and lower trachea, including four interferon stimulated proteins (OASL, MX1, IFIT3, and ISG15) and the GTPase, DRG2." (PMID 39247193, 2024). "Regarding OASL, its expression decreased by 2 log2 at homoeostasis and surged to a level 60 times higher 24 hours post-infection." (PMID 39300162, 2024). "As part of the anti-viral defense mechanisms in innate immunity, the expression level and activity of OASL varies in different cells based on cell type, tissue environment, and infection status." (PMID 39286258, 2024). "The results are consistent with the downregulation of IFN-β induced by the virus; aMPV/C infection significantly reduced poly (I·C)-induced OASL and MX1 mRNA." (PMID 36537793, 2023). "Infection with the YT strain upregulated the expression level of OASL, recording a 300-fold increase, whereas the level of MAVS was downregulated compared to that in the normal liver." (PMID 37063902, 2023). "To further confirm the replication ability of oncoVV-AVL and the variation in OASL after infection of oncoVV-AVL, we tested the expressions of A27L and OASL, the results showed that both A27L and OASL expressions were obviously upregulated." (PMID 35736181, 2022). "The previous research reported that IFIT1, IFIT2, IFTI3, IFIT3, IFI44, HERC4, and OASL genes are antitumoral effects and modulated the inflammatory response in cancer and infection." (PMID 35941292, 2022).
infection (continued). "The 2′-5′-oligoadenylate synthases (OAS1-3, OASL) were 1.6–7-fold induced upon infection to produce 2′-5′-adenylic acid as second messenger and activator of RNaseL for viral RNA degradation." (PMID 34777295, 2021). "OASL (fold change = 8.9) is a type I IFN inducible protein that inhibits viral replication during the early phase of infection by degrading viral RNA." (PMID 33897690, 2021). "Another group utilized a targeted approach to assess the role of OASL during infection with varied DNA viruses, and verified the importance of OASL in promoting DNA viral replication in vivo by using a murine model for OASL KO." (PMID 33362792, 2020). "To investigate the mRNA of PRRs, IFNs and ISGs in the spleens of H5N6 viruses infected geese, we quantified the mRNA expression of TLR7, TLR3, RIG-I, MDA5, IFN-α, IFN-γ, Mx, and OASL at 12 hours and 3 days post-infection with the two H5N6 viruses." (PMID 32046051, 2020). "OASL has been reported to exert antiviral as well as proviral function, depending on various mechanisms and phase of infection." (PMID 32545414, 2020). "OASL is expressed upon de novo infection with KSHV, but to date, the expression of OASL upon reactivation of KSHV-infected cells has not been well characterized." (PMID 29499066, 2018). "On the heels of this discovery, it was observed that this antiviral function is specific to infection with RNA viruses, however when challenged with a DNA virus, OASL exerts a prosurvival function through the inhibition of IFN I signaling." (PMID 28580319, 2017). "A search of the literature revealed the upregulation of OASL or the murine equivalent Oasl2 through transcriptome analysis in a number of infection models." (PMID 28580319, 2017). "H5N1 infection in DF-1 cells induced higher levels of Mx1 and OASL gene expression than H9N2 infection at 15 hpi (p value <0.01)." (PMID 25557928, 2015). "Furthermore, PPI network analysis revealed upregulation of oligoadenylate synthetase-like (OASL) following infection with various viruses, initiating a defense mechanism against infections." (PMID 41042757, 2025). "Interestingly, H7N1 infection led to enhanced OASL and IFNB expression levels at both MOIs similar to mock control groups pre-treated with butyrate." (PMID 39300162, 2024). "Besides, upon F48E9 infection, 9-butyl-harmol treatment increased the expression of OASL and MX1 to 2.51- and 3.13-fold, respectively." (PMID 36877059, 2023). "OASL did not exhibit a crucial role in TNF-mediated canonical necroptosis, whereas Oasl1+/+ and Oasl1–/– primary mouse fibroblasts exhibited pronounced differences in virus-induced necroptosis upon infection with wild-type MCMV (MCMV-WT) or MCMV-M45mutRHIM during a real-time cytotoxicity assay." (PMID 36604592, 2023). "In addition, OASL also responds to some cytosolic and vacuolar replicating bacterial pathogens, which showed that OASL played an essential role in the innate immune response to infection with a variety of pathogens." (PMID 34484305, 2021). "Intriguingly, we found that OASL enhanced infection of KSHV." (PMID 29499066, 2018). "Since this is the first study observing the OASL-(vacuolar) microbe link, the next question that arises is whether OASL is relevant during infection with other vacuolar pathogens and those which replicate in the cytoplasm." (PMID 28580319, 2017). "Thus during infection, OASL functions to enhance type I IFN signaling and suppress replication of RNA viruses." (PMID 28580319, 2017). "Expression of IFN-λ and some key ISG (OASL and Mx1) was induced in the early time and reached at their maximum value on day 2 post infection, and then started to decline gradually from day 3 post infection." (PMID 27449021, 2016).
infection (continued). "In addition to IFN-β, we observed that the expression of IFN-α, IL-28, MxA and OASL was also increased in NS1-S212P transfected cells comparing with that in NS1-WT transfected 293T cells after infection with WSN virus, while the expression of IL-29 and ISG15 was not influenced in these cells." (PMID 30285871, 2018). "Similarly, ISGs (IFIT1–2, GBP1, OASL) have been detected in MDMs 6 h post in vitro infection with ZEBOV-Mayinga (EBOV strain isolated in 1976) in the absence of increased IFNα/β expression." (PMID 29123522, 2017). "OASL may therefore play a critical role in defining the outcome of infection." (PMID 28580319, 2017). "Among others, 2’-5’ oligoadenylate synthetase-like (OASL), Interferon induced protein with tetratricopeptide repeats 2, 3 and 5 (IFIT2, IFIT3, IFIT5) were up-regulated in female-derived macrophages upon infection." (PMID 40794782, 2025). "Of these genes, 6 (OASL, IFI27, IFIT1, IFIT3, RSAD2and IFI44L) were in protein-protein interaction network and at each stage of infection." (PMID 40255307, 2025). "Transcriptome analysis of this study showed that untreated infection induces a strong ISG signature, including IFIT1–IFIT3, OASL, RSAD2, and MX1, consistent with canonical antiviral programs." (PMID 41480150, 2025). "We found that interferon-stimulated genes, crucial for restricting respiratory virus replication early after infection, such as CXCL10, CXCL9, CXCL11, OAS1, OASL, and ISG15, were significantly upregulated in PCLS 72 h post-infection." (PMID 41239423, 2025). "Two mRNAs were down-regulated in all treatment groups at the later time points post-infection, namely, CNTNAP1 and NR4A1, while twenty mRNAs were up-regulated in all later time point treatment groups, including IFI6, LY6E, MX1, OASL, STAT1, and CMPK2." (PMID 38675946, 2024). "While the number of significantly upregulated genes decreases to 37, these genes (e.g., ISG15, IFI6, IFI44L, HP, OAS1, IFI44, OASL, and IFI27) likely play a crucial role in the response to the progressing infection." (PMID 39282474, 2024). "We identified important genes DE in both our in vitro and in vivo infection models consistent with previous studies, namely, TLR3, IFIH1 (MDA5), SOCS1, OASL, DDX60, STAT1, MX1, CMPK2, LY96 (MD-2), STAT1, STAT2, TRIM25, IRF7, and IFIT5." (PMID 38675946, 2024). "H1N1 genome copies were also significantly decreased, while transcription of OASL and, to a lesser extent, IFNB were significantly enhanced by infection, particularly at an MOI of 0.1." (PMID 39300162, 2024). "Our study corroborates the antiviral activity of butyrate by demonstrating its modest, yet reproducible effect on H1N1 and H7N1 infection in CLEC213 cells, notably through a boost in OASL expression." (PMID 39300162, 2024). "OASL has been reported to lack OAS activity, but instead it can activate antiviral retinoic acid-inducible gene 1 (RIG-1) signaling after dsRNA infection." (PMID 37209263, 2023). "Infection with 60 ng/ml of HIV-1 for 24 or 48 h resulted in a significant increase in the expression of OAS1, OAS2, OAS3, and OASL at the mRNA level." (PMID 37209263, 2023). "We observed that SP600125 promoted the expression levels of IL-6, CCL21, IFN-β, MX, and OASL, but the expression level of IL-1β decreased in DEF cells in the presence of CHa strain infection." (PMID 35837399, 2022). "Infections also upregulate the gene expression of interferon-gamma (IFN-α) in the spleen and the antiviral proteins myxovirus-resistant 1, OASL, and IFN-induced transmembrane protein 3 in the spleen and kidney." (PMID 36072471, 2022). "Infection with the DPV CHv-BAC-ΔUL41 mutant virus induced more duck IFN-β and ISGs (Mx and OASL) production than DPV CHv-BAC parent virus infection in DEF cells." (PMID 35303942, 2022). "Compared to uninfected cells, the transcriptional response to infection including IFNβ, RIG-1, MDA-5, ISG15, and OASL was increased at 48 hpi, with IFNβ and OASL expression further increased following phenelzine treatment." (PMID 34031383, 2021).
infection (continued). "Transcriptome analysis of the nasal turbinates and lungs indicated that female ferrets had significant increases in interferon response genes (OASL, MX1, ISG15, etc.)on day 2 post infection which was delayed in aged males." (PMID 33469587, 2021). "In our study, the expression of IFN-α in the spleen and the expression of antiviral proteins (OASL, MX1, and IFITM3) in the spleen and kidney were increased after GNAstrV infection." (PMID 33647718, 2021). "The OASL gene was downregulated in the Ross [2x] group; however, it was upregulated in CEF cells infected with H5 viruses at 4 h post infection." (PMID 32381003, 2020). "We found that the mRNA expression levels of ZAP, MX2, MX1, PKR, OASL, and ISG15 were significantly higher in the Lp-1s treated group than in the TGEV infected group at various points after infection." (PMID 31781061, 2019). "Our findings indicate the molecular mechanisms involved in the switching of avian and mammalian OASL molecules to activate and enhance the OAS/RNase L and OASL/RIG-I pathways in response to infection by RNA viruses." (PMID 29973937, 2018). "We infected 293T OASL-/- cells reconstituted with either EV or hOASL with wildtype KSHVLYT and used flow cytometry to quantify the number of infected cells 24 h post infection." (PMID 29499066, 2018). "We then investigated the interaction between RIG-I and OASL and found that both dOASL and dOASL-3D* co-precipitated with dRIG-I in DF1 cells before and after infection with the CK/0513 virus." (PMID 29973937, 2018). "During infection with a KSHV ORF20stop mutant, however, OASL-dependent enhancement of infectivity was lost." (PMID 29499066, 2018). "Surprisingly, infection with viral dsDNA revealed an IFN inhibitory role and therefore pro-viral function of OASL through the inhibition of the cGAS cytosolic DNA sensing mechanism." (PMID 28580319, 2017). "PKR, IFI6, and OASL overexpression reduced the GFP expression level (and therefore infection) by more than 75% of the control." (PMID 27822537, 2016). "Early acute infection and A549 infected cells shared 150 upregulated genes including ATF3, a stress induced transcription factor, as well as other genes involved in the innate immune response such as MX1, DDX58/RIG-I, IFIT1, IFIT2, DHX58/MDA5, and OASL." (PMID 39065267, 2024). "By 72 h post-infection, although only five common genes (IFI44, OASL, OAS3, IRF9, IRF7) are identified, these genes contribute significantly to a range of crucial GO processes, emphasizing the depth of the immune response despite the limited number of genes involved." (PMID 38957806, 2024). "For example, 48 h after infection, the transcription levels of OASL, Mx, MDA5, and MAVS were upregulated in the FAdV-4 GY single-infected group (group A) and the group subjected first to FAdV-4 GY infection with aHEV-YT and then infection with aHEV-YT (group C) after culturing with LMH cells." (PMID 37896849, 2023). "After 48 h of infection, LMH cells infected with FAdV-4 GY (group A) showed significant upregulation of the transcription levels of most immuno-cytokines (IL18, TLR7, IFN-α, and IFN-β excepted), such as OASL, Mx, MDA5, and MAVS." (PMID 37896849, 2023). "In contrast to changes in mRNA levels, protein levels of OAS2 and OAS3 remained elevated in infected pericytes even after 48 and 72 h post infection, and OASL protein expression did not change as the result of infection." (PMID 37209263, 2023). "Numerous ISGs activated by 85-7C40 showed antiviral effects against the wild-type strain infection, particularly the IFI44 (an ISG upregulated specifically by the 85-7C40 infection) and OASL (upregulated higher in 85-7C40 than 85-7-infected cells), exhibited powerful antiviral activity." (PMID 35762780, 2022).
infection (continued). "The authors also reported infection-mediated upregulated expression of IFN-β, inflammatory cytokines (IL-8, tumor necrosis factor-alpha), antiviral proteins (Mx, OASL, and double-stranded RNA-dependent protein kinase), and major histocompatibility complex class I." (PMID 36072471, 2022). "Given that ISGs such as ISG15 and OASL were downregulated, we postulated that the JAK-STAT signaling cascade pathway might be influenced by the infection of oncoVV-WCL." (PMID 34064193, 2021). "Upon VACV strain infection, the HD11 cells produced IFNβ, OASL, IL-1β, and IL-8 transcripts." (PMID 32660114, 2020). "Our data show that OASL is beneficial for both MHV68 and KSHVLYT infection." (PMID 29499066, 2018). "To verify the antiviral function of OASL in a reconstitution assay, we infected 293T OASL-/- cells reconstituted with EV or hOASL with vesicular stomatitis virus expressing GFP (VSV-GFP) and determined the GFP signal by flow cytometry 16 h post infection." (PMID 29499066, 2018). "However, when we infected OASL-reconstituted OASL-/- cells with VSV-GFP, we observed inhibition of infection as expected." (PMID 29499066, 2018). "We then reconstituted 293T OASL-/- cells with mOASL1 or hOASL, infected them with MHV68-GFP at a high MOI, and quantified the number of infected GFP-positive cells by flow cytometry 20 h post infection." (PMID 29499066, 2018). "Although, this search was not exhaustive, it suggests that OASL more than likely plays a role during infection with a wide range of bacterial species." (PMID 28580319, 2017). "In addition, expression of two key ISG, Mx1 and OASL, was also examined by quantitative real time PCR during the ATMUV infection." (PMID 27449021, 2016). "Also, it was important to discuss thatthough our study identified a total of 9 genes that were common among three stages, but only 6 of them (OASL, IFI27, IFIT1, IFIT3, RSAD2and IFI44L) made into the PPI network whose expression level increases with the increase in the level of infection." (PMID 40255307, 2025). "Similarly, infection with ATMUV resulted in robust expression of Mx1 and OASL." (PMID 27449021, 2016). "However, upon infection with the Sendai virus (SeV), the cells exhibited increased expression of IFN and chemokine genes (IFNB1, IL29, IL28A, IL28B and CXCL11) and interferon-stimulated genes (DDX58, IFIH1, DHX58, IFIT1-3, and OASL)." (PMID 20661427, 2010). "We also examined IFN-stimulated proteins whose induction was suppressed by infection, but not by heat-inactivated virions or upon inhibition of viral DNA replication (ISG20, OASL, ZNFX1)." (PMID 38065956, 2023). "In monocytes or macrophages, SP600125 treatment also promoted the expression levels of IFN-β, MX, and OASL, but not CCL21, under CHa strain infection." (PMID 35837399, 2022). "Regardless of dexamethasone treatment or time post-infection, expression of ISGs of the OAS family, specifically OAS2, OAS3 and OASL, and its downstream RNaseL, were highly upregulated." (PMID 31635289, 2019). "We found that ISG15, OASl-1, and RNF185 were induced in A549 cells infected with D39 at 1 h, but not 5 h post-infection." (PMID 30984149, 2019). "When we infected hOASL-reconstituted 293T OASL-/- cells with KSHVLYT ORF20stop, we did not observe enhancement of infection." (PMID 29499066, 2018). "This is what is observed during infection with HSV and Vaccinia DNA viruses, however an identical response cannot be assumed since it was determined that OASL knock-down did not influence IFN-β release during M. leprae infection." (PMID 28580319, 2017). "Interestingly, the expression of MX2, IFIT2, OASL and OAS2 was up-regulated after infection with HEV-3f in both pig livers and HepaRG cells but not in pig livers infected with HEV-3c." (PMID 38058490, 2023).